NFAT5 (nuclear factor of activated T cells 5)
Diseases named in the same sentence as NFAT5 in open-access papers (continued):
Sharing a sentence is not in itself a finding about the gene and the disease.
glioma (9 papers, 2017 to 2023). A benign or malignant brain and spinal cord tumor that arises from glial cells (astrocytes, oligodendrocytes, ependymal cells). "Meanwhile, 62.5% (35/56) glioma specimen with high NFAT5 K668 methylation levels displayed enhanced protein expression of EGFR pY1068." (PMID 37429858, 2023). "The median survival durations of glioma patients harboring tumors with low and high NFAT5 expression were 19.9 and 9.8 months, respectively, and 21.5 and 8.1 months for patients with IDH wild-type GBM, respectively." (PMID 37429858, 2023). "A total of 57.1% (32/56) glioma specimens with high NFAT5 K668 methylation levels displayed enhanced protein expression of EZH2 pS21." (PMID 37429858, 2023). "NFAT5 expression levels were significantly elevated in GBM tissues compared with those in low-grade gliomas (LGGs) and adjacent NBs." (PMID 37429858, 2023). "Consistently, a previous study has underpinned that NFAT5 is a target gene of miR-31 in glioma cells." (PMID 36311041, 2022). "Nuclear factor of activated T cell 5 (NFAT5) is involved in neuroinflammation, and NFAT5 levels correspond to glioma pathological grade." (PMID 34804019, 2021). "Consistent with the immunohistochemistry results, Western blot assay showed that NFAT5 levels were elevated in glioma tissues and were correlated with the pathological grade." (PMID 28983240, 2017). "In this study, NFAT5 and SBF2-AS1 was highly expressed in glioma samples and positively associated with glioma WHO grades." (PMID 28983240, 2017). "In this study, the transcription factor nuclear factor of activated T-cells 5 (NFAT5) was significantly elevated in glioma samples and GBM cell lines, and positively correlated with glioma WHO grades." (PMID 28983240, 2017). "Downregulation of NFAT5 or SBF2-AS1 decreased the microvessel density of xenograft gliomas and NFAT5 knockdown combined with SBF2-AS1 knockdown presented the lowest microvessel density." (PMID 28983240, 2017). "Finally, due to their role in promoting the cell cycle of gliomas, NFAT5 and E2F5 TFs are downregulated in seven days for the D-GSC#83 and D-GSC#1 lines, respectively." (PMID 34440820, 2021). "But the expression levels of NFAT5 in gliomas and its potential role in GBM angiogenesis still remain unclear." (PMID 28983240, 2017). "NFAT5/SBF2-AS1/miR-338-3p/EGFL7 pathway may provide novel targets for glioma anti-angiogenic treatment." (PMID 28983240, 2017). "In conclusion, increased NFAT5 levels were positively correlated with glioma pathological grade." (PMID 28983240, 2017). "However, the proportion of NFAT5-positive cells and the staining intensity were higher in glioma sections and presented a tumor pathological grade-dependent pattern." (PMID 28983240, 2017). "Results showed that the volume of xenograft gliomas were dramatically reduced in NFAT5(-) group, SBF2-AS1(-) group, and NFAT5(-)+SBF2-AS1(-) group compared with NFAT5(-)NC+SBF2-AS1(-)NC group." (PMID 28983240, 2017). "In this study, the expression levels of NFAT5 and SBF2-AS1 were investigated in glioma samples and GBM cell lines." (PMID 28983240, 2017). "To determine the clinical significance of NFAT5, we analyzed the NFAT5 levels in 83 glioma specimens and adjacent non-tumor brain (NB) tissues obtained from the Tianjin Huanhu Hospital." (PMID 37429858, 2023). "During the formation and growth of glioma, miR-21 in glioma-derived exosomes can directly downregulate targets such as BTG 2, PDCD 4 and NFAT5, thereby expanding the infiltration range and increasing the proliferation rate of microglia, the innate immune cells of the nervous system." (PMID 36865549, 2023). "LncRNA NFAT5 and LSINCT5 are up‐regulated in glioma and promote the proliferation of glioma." (PMID 33336871, 2021). "Furthermore, knockdown of both NFAT5 and SBF2-AS1 inhibited the xenograft glioma growth and reduced the microvessel density." (PMID 28983240, 2017). "The combination knockdown of NFAT5 and SBF2-AS1 produced the minimum xenograft glioma volume." (PMID 28983240, 2017).
glioma (continued). "To determine the clinical significance of EGFR/EZH2 dependent NFAT5 lysine methylation in glioma, we performed IHC analysis to examine the expression and correlation between EZH2 pS21 and Me3-NFAT5 K668 as well as EGFR pY1068 levels in 83 human glioma specimens." (PMID 37429858, 2023).
lung adenocarcinoma (8 papers, 2017 to 2025). A carcinoma that arises from the lung and is characterized by the presence of malignant glandular epithelial cells. "In the lung adenocarcinoma cells, the decreased expression of NFAT5 lowers the proliferation and migration of cells, which is accompanied by a considerable decrease in the expression of AQP5." (PMID 36766810, 2023). "NFAT5 was shown to be up-regulated in lung adenocarcinoma cells, and the knockdown of NFAT5 decreased the proliferation and migration of these cells." (PMID 29448950, 2018). "Moreover, overexpression of NFAT5 promoted the proliferation and migration of lung adenocarcinoma cells, which coincided with a considerable increase in the expression of AQP5." (PMID 36766810, 2023). "Moreover, inhibiting NFAT5 expression reduces the proliferation and migration of lung adenocarcinoma cells, which is accompanied by suppressing the expression of aquaporin-5 (AQP5), a water transporter depending on the osmotic gradient." (PMID 30873159, 2019). "Therefore, this study investigated the effects of macrophages and TonEBP/NFAT5 expression on cisplatin resistance and migration in A549 lung adenocarcinoma cells." (PMID 38438872, 2024). "Nuclear factor of activated T cells 5 (NFAT5) upregulated Aqp5 mRNA levels in chronic lymphocytic leukemia B cells (MEC-1 cells) and B cells isolated from patients with chronic lymphocytic leukemia, lung adenocarcinoma cells." (PMID 36768212, 2023).
Sepsis (8 papers, 2015 to 2025). Sepsis is defined as life-threatening organ dysfunction caused by a dysregulated host response to infection. "MiR-223 was found to alleviate sepsis by binding to the mRNA of NFAT5 and Rasa1 and causing IL-4-meditated M2 macrophage differentiation." (PMID 34956210, 2021). "For instance, in studies on sepsis-induced acute kidney injury, NFAT5 has been found to play a crucial role in renal collecting duct cells." (PMID 40076009, 2025). "NFAT5 also plays a pivotal role in sepsis by binding to the TNFα promoter, interacting with NFκB p65, and recruiting the p300 subunit, thereby enhancing LPS-induced inflammation." (PMID 40421201, 2025). "Sepsis-induced urinary concentration defect is related to NO-dependent inactivation of TonEBP/NFAT5, which down-regulates renal medullary solute transport proteins and aquaporin-2." (PMID 35722824, 2022). "A separate study showed a role for miR-223-Rasal/NFAT5 axis in mediating macrophage polarization during sepsis." (PMID 34956210, 2021). "Indeed, miR-223 was a critical factor in regulating IL-4-induced M2 differentiation of macrophages by controlling Nfat5 and Rasa1 protein production, thus modulating the pathophysiology of sepsis." (PMID 34956210, 2021). "Additionally, in a murine sepsis model, NFAT5 expression decreases alongside a rise in M2 macrophages, a process associated with miR-223 regulation, a key factor in IL4-driven M2 polarization, indicating that NFAT5 regulates anti-inflammatory macrophage responses." (PMID 40421201, 2025).
lung cancer (7 papers, 2017 to 2025). A malignant neoplasm involving the lung. "A recent study showed that the survival rate of patients with lung cancer is linked to TonEBP/NFAT5 expression." (PMID 38438872, 2024). "TonEBP/NFAT5 expression is closely associated with the survival rate of patients with lung cancer." (PMID 38438872, 2024). "The survival rate of patients with lung cancer was considerably lowered with increased TonEBP/NFAT5 expression." (PMID 38438872, 2024). "As reported, circ_0001944 contributed to glycolysis and tumor development by up‐regulating NFAT5 as a decoy for miR‐142‐5p in non‐small cell lung cancer." (PMID 36597856, 2023). "LncRNA RMRP enhances invasion, migration, and proliferation of nonsmall cell lung cancer cells by the miR-613/NFAT5 axis." (PMID 35132320, 2022). "In lung cancer, overexpression of nuclear factor of activated T cells 5, also known as NFAT5, intimately interacts with AQP5, increasing AQP5 expression in order to promote cell proliferation and migration." (PMID 30555637, 2018). "In addition, macrophages increase TonEBP/NFAT5 expression, which is an important regulator of the malignant transformation of lung cancer cells." (PMID 38438872, 2024). "Hence, NFIX with IL6ST, TIMP1, ITGB1, PTCH1, GGCX and NFAT5 genes may regulate the migration and invasion process and they could serve as potential therapeutic targets in patients with lung cancer to predict survival and improve prognosis." (PMID 28871224, 2017).
pancreatic cancer (7 papers, 2019 to 2024). "Further, TGFβ1 was recently shown to induce a novel complex composed of NFAT5, Smad3, and Smad4, which promotes epithelial-to-mesenchymal transition in pancreatic cancer cells." (PMID 39595620, 2024). "NFAT5 is upregulated in pancreatic cancer cells and promotes aerobic glycolysis by inducing phosphoglycerate kinase 1 (PGK-1)." (PMID 36077186, 2022). "For example, NFAT5 was proved to conduce to the glycolytic phenotype rewiring and pancreatic cancer progression through transcription of PGK1." (PMID 32863773, 2020). "To study the effect of NFAT5 on PDAC, we examined the expression level of NFAT5 in six pancreatic cancer cell lines both at the mRNA and protein level, at which AsPC-1 and BxPC-3 exhibit the highest expression." (PMID 31827081, 2019). "In our study, we demonstrated that NFAT5 contributes to glycolytic phenotype rewiring and pancreatic cancer progression via transcription of PGK1." (PMID 31827081, 2019). "Our study demonstrated that NFAT5 is upregulated in pancreatic cancer cells, and NFAT5 facilitates PDAC cell survival via contributing to the Warburg effect by transcription of PGK1." (PMID 31827081, 2019). "Three datasets closely related to the Warburg effect (glycolysis, PI3K/AKT/mTOR signaling, and mTORC1 signaling) were enriched in the NFAT5 high-expression group, indicating that NFAT5 may have an impact on glucose metabolism in pancreatic cancer." (PMID 31827081, 2019). "Then, we tested the expression status of NFAT5 by IHC staining and analyzed its correlation with 18F-FDG uptake in 39 pancreatic cancer patients who received PET-CT examination to validate our results in clinical samples." (PMID 31827081, 2019). "To understand how NFAT5 influences pancreatic tumor cell growth, we first performed Geneset Enrichment Analysis (GSEA) by dividing samples into two groups based on NFAT5 expression in the Renji cohort." (PMID 31827081, 2019).
viral infection (7 papers, 2012 to 2025). "NFAT5 plays a multifaceted role in inflammation, acting as both a promoter of immune responses and, paradoxically, a facilitator of viral infections." (PMID 40421201, 2025). "Relative to the mock-infected controls, NFAT5 protein levels were decreased by ~40% after viral infection, suggesting that virus infection decreased accumulation of NFAT5 in mitochondria." (PMID 37227295, 2023). "Relative to the uninfected cells, mRNA levels of NFAT5 significantly increased by approximately 3.87-fold following virus infection." (PMID 37227295, 2023). "Nuclear NFAT5 proteins were evenly dispersed following virus infection, with only a small amount of speckle-like staining left in the cytoplasm." (PMID 37227295, 2023). "Here, for the first time, we showed that NFAT5 is involved in BoHV-1 productive infection as virus infection relocalized NFAT5 and reduced accumulation of NAFT5 proteins in both cytoplasm and mitochondria (–, 4)." (PMID 37227295, 2023). "NFAT5 proteins were readily detected in mitochondria in mock-infected cells, and their protein levels were significantly reduced after viral infection." (PMID 37227295, 2023). "While NFAT5 is widely known to be involved in hypertonic stress responses, there is substantial evidence that illustrates its role in modulating viral infections." (PMID 34064510, 2021). "Instead, we will summarize the recent progress in NFAT5 expression regulated by miRNA/lncRNA targeting, epigenetic modifications and viral infections, as well as the related signal transduction pathways." (PMID 34064510, 2021). "In contrast, the expected full-length NFAT5 was increased in the nucleus following virus infection." (PMID 37227295, 2023). "Taken together, NFAT5 is a potential host factor that restricts BoHV-1 productive infection, and virus infection hijacks NFAT5 signaling transduction by relocalization of NFAT5 molecules in cytoplasm, nucleus, and mitochondria, as well as altered expression of its downstream targets." (PMID 37227295, 2023). "Immunofluorescence assays revealed a speckle-like staining pattern, particularly for cytoplasmic NFAT5 in the mock-infected cells, and we hypothesized that NFAT5 may be localized to mitochondria and altered by viral infection." (PMID 37227295, 2023). "At the same time, the virus infection increased NFAT5 transcription." (PMID 37227295, 2023). "In addition, the protein levels of major NFAT5 bands were decreased in cytosol fractions attributed to virus infection." (PMID 37227295, 2023). "Importantly, we found a subset of NFAT5 resides in mitochondria, and virus infection led to the depletion of mitochondrial NFAT5." (PMID 37227295, 2023). "Because virus infection not only has an influence on the nuclear accumulation of NFAT5 protein but also relocalized nuclear NFAT5 proteins, we wondered whether the activity of NFAT5 protein was therefore influenced." (PMID 37227295, 2023). "Interestingly, for the first time, we found that NFAT5 restricts BoHV-1 productive infection, and virus infection affects NFAT5 signaling transduction via various approaches." (PMID 37227295, 2023). "Virus infection relocalized NFAT5 protein and decreased the cytosol accumulation." (PMID 37227295, 2023). "Given that nuclear translocation of NFAT5 may enhance its transcriptional activity, we examined the effects that virus infection had on the accumulation of nuclear NFAT5 proteins." (PMID 37227295, 2023). "Moreover, we found two NFAT5 isoforms with distinct molecular weights were exclusively detected in the nucleus, where the accumulation was differentially affected following virus infection, representing a novel regulation mechanism on NFAT5 function in response to BoHV-1infection." (PMID 37227295, 2023). "In addition to full-length NFAT5, another two isoforms with distinct molecular weights were exclusively detected in the nucleus, where the accumulation was differentially affected following virus infection." (PMID 37227295, 2023).
viral infection (continued). "The mRNA levels of the canonical downstream targets regulated by NFAT5 signaling, including PGK1, SMIT, and BGT-1, were differentially altered by virus infection with unexpected manners." (PMID 37227295, 2023). "Some proximal genes targeted by these 6 REs (FSCN1, GSTP1, JAM3, CHRNA6, NFAT5, and PRRC2A) are related to immune response, viral infection, and/or HCC based on ontological analysis." (PMID 31639042, 2019). "In addition, virus infection differentially altered mRNA levels of PGK1, SMIT, and BGT-1, the canonical downstream targets regulated by NFAT5." (PMID 37227295, 2023). "Nuclear factor of activated T cells 5 (NFAT5) is known to be involved in the response to high salt concentration in body fluids but its role in viral infection is not currently understood." (PMID 29220410, 2017). "Therefore, the unaltered measurable NFAT5 protein levels do not correspond to the increased mRNA levels in response to virus infection." (PMID 37227295, 2023). "At day 11 post-viral infection, wild-type HIV-198IN22 replication was greater, but not significantly so, as compared to replication of HIV-198IN22 NFAT5-Mut." (PMID 22496647, 2012).
acute kidney injury (6 papers, 2019 to 2025). Sudden and sustained deterioration of the kidney function characterized by decreased glomerular filtration rate, increased serum creatinine or oliguria. "Some studies suggest that NFAT5 provides protection against acute kidney injury, while others indicate the opposite effect." (PMID 39874047, 2025). "In kidney pathophysiology, NFAT5 expression declines alongside AQP2 and endothelial NOS (eNOS) in the renal medulla during acute kidney injury in rodent models, emphasizing the importance of spatiotemporal regulation in renal injury progression." (PMID 40421201, 2025).
Hypernatremia (6 papers, 2016 to 2025). An abnormally increased sodium concentration in the blood. "Both acute (6 or 24 hours) and chronic (over 7 days) hypernatremia conditions increase NFAT5-associated NOS2 expression and NO production in microglia, which is correlated with intracellular calcium dynamics." (PMID 40421201, 2025). "Defective proliferative capacity of NFAT5-deficient T cells was also observed in vivo in experiments in which wild-type and NFAT5-deficient T cells were adoptively transferred in NFAT5-null host mice which suffer pathological hypernatremia." (PMID 30949179, 2019). "In vivo, levels of hypernatremia sufficient to activate NFAT5 have been observed in different conditions." (PMID 30949179, 2019). "ROS are also produced in macrophages exposed to hypernatremia or LPS and neutralizing them affects variably the ability of NFAT5 to induce several target genes." (PMID 30949179, 2019). "In T cells exposed to hypernatremia, NFAT5 helps maintaining proliferative capacity, homeostatic survival, and the balance of naïve and memory T cells." (PMID 30949179, 2019). "Intriguingly, NFAT5 itself can influence systemic tonicity and NFAT5-null mice were found to exhibit plasma hypernatremia and hyperosmolality (between 370 and 420 mOsm/kg)." (PMID 30949179, 2019). "NFAT5 was also recently shown to enhance expression of IL-2 mRNA in activated primary mouse CD4 T cells exposed to hypernatremia." (PMID 30949179, 2019). "Hypernatremia also promotes polarization of antigen-activated T lymphocytes toward Th17 cells in an NFAT5-dependent manner." (PMID 30949179, 2019). "CD24 is expressed at low levels in activated T cells, but is induced in an NFAT5-dependent manner under osmotic stress, even in moderate hypernatremia (380 mOsm/kg)." (PMID 30949179, 2019). "The ability of leukocytes to respond to hypernatremia and express cytokines had already been reported in the 1990's, and early works on NFAT5 showed that it could induce TNFα and lymphotoxin-β in the human T cell line Jurkat cultured in high-sodium medium." (PMID 30949179, 2019). "Furthermore, Nfat5-null mice had hypernatremia and T cell lymphopenia, whereas T cell-specific Nfat5 knockout mice had isotonic plasma and normal T cell numbers, but decreased survival and proliferation in hypertonic condition." (PMID 30538703, 2018). "Hypertonicity-activated NFAT5 also enhances the expression of the Th17 master transcription regulator RORγt, to whose promoter NFAT5 is recruited in mouse CD4 T cells exposed to hypernatremia, and induces IL-23R in a RORγt-dependent manner." (PMID 30949179, 2019). "Mice without NFAT5 expression suffer from constitutive, pronounced hypernatremia and manifest severe immunodeficiency, with T cell lymphopenia, altered naive/memory T cell homeostasis, and inability to reject allogeneic tumors." (PMID 27833920, 2016).